LINC00396 (long independently transcribed non-coding RNA 396)
Gene: Long non-coding RNA gene on chromosome 13 (110,053,285 to 110,054,952, forward strand). Ensembl gene ENSG00000231428.
Diseases named in the same sentence as LINC00396 in open-access papers:
LINC00396 is named in the same sentence as 1 disease in open-access papers, as found by Europe PMC text mining. Sharing a sentence is not in itself a finding about the gene and the disease. The quoted sentences say what the papers report.
lung carcinoma (1 paper, 2023). "To map the location of LINC00963, we applied FISH and detected cytoplasmic expression of LINC00396 both in LUAD tissues as well as in lung cancer cells." (PMID 36604626, 2023).